CASP4 (caspase 4)
Diseases named in the same sentence as CASP4 in open-access papers (continued):
Sharing a sentence is not in itself a finding about the gene and the disease.
infection (continued). "Notably, the studies point to a specific importance for caspase-4 in mucosal immunity since caspase-4 expression level and ability to be activated in response to infection highly differs compared with caspase-5." (PMID 26426007, 2015). "Thus, it is plausible that CASP4/11 is activated by oxidized phospholipids during infection." (PMID 35588457, 2022). "Since caspase-1 inhibitor AC-YVAD-CMK also shows inhibitory activity against caspase-4 and caspase-5, which also belong to inflammatory caspases, we asked the question whether caspase-1 plays a prominent role in pyroptosis during the infection of CVB3 and EV71." (PMID 29440739, 2018). "Despite both caspase-4 and -5 possessing the ability to bind LPS, caspase-5 expression is inducible by LPS similar to caspase-11; however caspase-4 is constitutively expressed in human epithelial cells and is reported to be only modestly induced upon infection." (PMID 26426007, 2015). "Infection with mT3Sf::empty induced cell death of infected THP-1 human macrophages, and this death was reduced in CASP4/NLRC4–/– double knockout cells to the background levels seen in control GSDMD–/– cells." (PMID 41533441, 2026). "Apoptosis related proteins (ANXA5 and Caspase-13/CASP4) and CAPN14, USP18, XAF1, Caspase-13/CASP4, and ISG12 transcripts were significantly upregulated after infection with swH1N1 compared to controls." (PMID 39247193, 2024). "The transcription factors IRF1 and IRF2 mediate non-canonical inflammasome activation by driving the expression of CASP4 and GSDMD genes at steady state and during infection." (PMID 38106412, 2023). "Together, these data indicate that caspase-1, caspase-4, and caspase-5 are processed into their mature forms upon IFN-γ priming and infection with T4SS+ Lp." (PMID 37737612, 2023). "Cell death and IL-18 release were significantly reduced in unprimed and IFN-γ-primed hMDMs treated with CASP4 or both CASP4 and CASP5 siRNA prior to infection with T4SS+ Lp, compared to control siRNA-treated cells." (PMID 37737612, 2023). "We find that although the NAIP/NLRC4 inflammasome is essential for detecting T3SS ligands in human macrophages, it is partially required for responses to infection, as Salmonella also activated the NLRP3 and CASP4/5 inflammasomes." (PMID 35073381, 2022). "Rather, we found that infection of human macrophages with Salmonella grown under SPI-1-inducing conditions activates multiple inflammasomes, including NAIP/NLRC4, CASP4/5, and NLRP3." (PMID 35073381, 2022). "Several recent studies found that caspase and caspase 4 of F. merguiensis, caspase 2 of L. vannamei and caspase 1 of P. monodon were all up-regulated in the hemocytes after DIV1 infection." (PMID 34512588, 2021). "To this end, our RT-PCR results were in agreement with the microarray data and we observed differential expression of caspase-1, caspase-4, and caspase-8 and NLRP3 in MDR-PA induced infection." (PMID 35046947, 2021). "This was in agreement with our finding that the pro-apoptotic genes CASP1, CASP4, and CASP7 were increased during infection." (PMID 32093375, 2020). "UPEC significantly decreased the gene expression of CASP4, NLRP1, NLRC4, NLRP6 and AIM2 at MOI 1 and MOI 10 after 3 h of infection compared to unstimulated cells." (PMID 33318544, 2020). "Upon infection with either EPEC WT or EPEC-1, cell death was suppressed by caspase-4 siRNA, suggesting that Tir-induced cytotoxicity is mediated by caspase-4-driven pyroptosis." (PMID 33378358, 2020). "Because E. tarda hemolysin was largely associated with OMVs and critically involved in caspase-4-dependent inflammasome activation, it raises the possibility that E. tarda employs hemolysin-associated OMVs to activate the non-canonical inflammasome during infection." (PMID 30138458, 2018).
infection (continued). "In comparison with wild-type bacteria, infection with the complemented PA14 ΔflgK pUCP19-flgK and PA14 ΔpopB pUCP19-popB strains restored to varying degrees the protein levels of TLR4, TLR5, NLRC4, caspase-4 and mature IL-1β and IL-18." (PMID 28469996, 2017). "Various caspases, including the subfamily of inflammatory mediator (CASP1, CASP4), the apoptotic activator (CASP2, CASP8) and the apoptotic executioner (CASP7) were up-regulated in response to infection." (PMID 21110886, 2010). "The elevated levels of these chemokines in the absence of caspase-4 suggest that caspase-4 plays a regulatory role in limiting excessive immune recruitment, preventing hyperinflammatory responses during infection." (PMID 40137780, 2025). "In this study, we found that in the infection model of THP-1 derived human macrophages, which express multiple inflammasomes, E. tarda induced pyroptosis in a manner that depended on NLRC4, NLRP3, ASC, Casp1, and Casp4." (PMID 39951384, 2025). "Our results indicate that, for infection with M. tuberculosis or M. kansasii, sensing of the infection by the non-canonical pathway is essential for host inflammasome responses, since caspase-4/5 are required for IL-1β release." (PMID 40272180, 2025). "In WT THP-1 macrophages, specific to infection with M. tuberculosis was a small amount of caspase-4 processing and release that was not blocked by inhibition of NLRP3 with MCC950." (PMID 40272180, 2025). "The NLRP11−/− and NLRP11∆N_LRR mutants, but not the NLRP11∆PYD mutant, also displayed reduced activation of caspase-4 during infection with the intracytosolic, gram-negative pathogen Shigella flexneri." (PMID 40272180, 2025). "Caspase-1, caspase-4, and caspase-11 cleave the GSDMD in response to infection." (PMID 38429762, 2024). "We also demonstrate that DCA mediated lncRNA57RIK can induce the binding of caspase-4/11 with GBPs to activate caspase-4/11 by LPS, and also is necessary for Gram-negative bacterium mediated infection." (PMID 39664579, 2024). "Although Caspase-3 and Caspase-4 regulated epithelial cell death during STM infection, inhibition of either Caspase-3 or -4 did not fully reverse the reduction in intracellular bacterial burden that was caused by PMNs." (PMID 36191054, 2022). "Furthermore, we confirmed that infection of human blood neutrophils with two different Pseudomonas aeruginosa strains (PAO1 and CHA) also triggered a Caspase-1-dependent, yet Caspase-4/5, -3/7 and -8-independent, IL-1ß release and neutrophil lysis." (PMID 35849616, 2022). "NAIP-/- and NLRC4-/- THP-1s treated with CASP5 siRNA showed a slight but significant decrease in IL-1β secretion following CASP5 siRNA treatment, but not CASP4 siRNA treatment, compared to control siRNA-treated cells following WT Stm infection." (PMID 35073381, 2022). "We found the same to be true for caspase-4 activation after 4 and 6 h of CFT073 infection." (PMID 34944029, 2021). "Here, we found that in vivo infection with either P. vivax or P. falciparum is sufficient to activate caspase-4 and cleave GSDM-D in monocytes without exposure to LPS." (PMID 32929083, 2020). "In order to gain mechanistic insights of Tir-induced caspase-4 activation, we performed proteomics analysis of SNU-C5 cells following infection of unprimed and IFNγ-primed cells with EPEC-0, EPEC-2, EPEC-1-TirAA-EspZ, EPEC-1, and EPEC-1-TirAA, using isobaric labelling." (PMID 33378358, 2020). "In rodents, the activation of caspase-1 provoked the release of IL-18 which, in turn, induced IFN-γ to prime caspase-11 activity, whereas caspase-4 transgenic mice did not necessitate IFN-γ priming upstream of caspase-4 to control the infection." (PMID 33329561, 2020). "After 6 h of hCFs infection with wild-type PAO1 and PA14, significant levels of TLR4, TLR5, NLRC4, native form of caspase-4 and IL-1β and IL-18 mature-formed proteins were detected by western blot with quantification of protein densitometry ratios relative to endogenous β-actin." (PMID 28469996, 2017).
infection (continued). "Late il-1β expression in lethally infected mice correlated with an early higher expression of caspase 1 and caspase 4 (also known as caspase 11) on day 3 p.i. compared to nonlethal infection." (PMID 23526993, 2013). "Although the caspase-4 change did not meet the 2-fold threshold, it is notable because prior studies have linked RSV-induced syncytium formation to apoptosis in the later stages of infection, possibly via intrinsic pathways." (PMID 40630640, 2025). "Moreover, we have also observed that the expression levels of caspase 4 are higher between 96 and 228 h following WSSV infection, leading us to speculate that this gene plays a more crucial role in the later stages of WSSV infection." (PMID 38732180, 2024). "The mechanistic insight into caspase-4 activation pathways described herein delivers new understanding of the molecular processes controlling protective responses during infection, and the pathological inflammatory responses driven by noncanonical inflammasome signalling." (PMID 37558421, 2023). "In the infection context, only C. violaceum that expressed exogenous CopC could induce weak modification of caspase-11 but not caspase-4." (PMID 35446120, 2022). "T. gondii tachyzoites did not induce caspase 4/5 production after 2 h of infection." (PMID 34607465, 2021). "Whether caspase-4/-11 could also serve as a guardian of the host cytoskeleton during infection by Gram-negative bacteria will need further study." (PMID 31018119, 2019). "Furthermore, caspase-4 activation in human macrophages has also been detected after infection with the different Gram negative bacteria Legionella pneumophila, Yersinia pseudotuberculosis and Salmonella enterica serovar Typhimurium." (PMID 28469996, 2017). "Furthermore, intracellular HAdV DNA level in siCASP4+5 vs siNC-transfected and siGSDMD vs siNC-transfected dTHP-1 cells are comparable at different timepoints post-infection, indicating that silencing of caspase-4/5 and GSDMD did not affect the HAdV replication." (PMID 37180156, 2023). "We report the discovery of fundamental roles for the noncanonical inflammasome molecule Caspase-4/11 in promoting pathological inflammatory and prothrombotic pathways in severe acute respiratory syndrome coronavirus 2 (SARS–CoV-2) infections." (PMID 35588457, 2022). "Notably, Δ6 Yptb infection led to robust GSDMD cleavage in WT Caco-2 cells, which was completely absent in CASP4−/− Caco-2 cells, indicating that caspase-4 is required for GSDMD cleavage in human IECs in response to Yersinia lacking its secreted effectors." (PMID 37615436, 2023). "Additionally, the Western blot analysis of caspase cleavage demonstrated that infection by E143K SRIP, but not WT or N139S SRIPs, induced the activation of caspase 4, not caspases 1 and 3 in TE671 and SF268 cells." (PMID 35891552, 2022). "Remarkably, oxidized phospholipids induce a CASP4/11-dependent cytokine response without inducing GSDMD-dependent cell death, thus mirroring our in vivo results in which Casp11−/− mice fare better during infection while Gsdmd−/− mice do not." (PMID 35588457, 2022). "Furthermore, we observed that B. thailandensis infection resulted in caspase-4 activation only in IFN-γ-primed cells (p32 fragment), which is in accordance with what has been observed during infection of epithelial cells with other cytosolic Gram-negative bacteria." (PMID 34399626, 2021).
cancer (44 papers, 2009 to 2025). A tumor composed of atypical neoplastic, often pleomorphic cells that invade other tissues. "The results showed that the expression levels of IL-6, IL18 and GSDME were positively associated with these compounds, while CASP4 was positively correlated with sensitivity to 26 cancer drugs." (PMID 35246158, 2022). "The expression of CASP4 in human cancer samples and its association to patient prognosis has been poorly investigated however some data are already available." (PMID 30531914, 2018). "We found that CASP4 expression was strongly correlated with the level of immune cell infiltration in many cancers, including colon, hepatocellular liver, squamous lung, testicular, and prostate cancers." (PMID 39075190, 2024). "This indicated that inhibiting CASP4 expression increases the sensitivity of cancer cells to most chemotherapeutic agents." (PMID 39075190, 2024). "Our result identified the FADD, TNFRSF1A, CASP9, MLKL, and CASP4 involved in the PANoptosis process and significantly affect patient survival, which can provide future direction in cancer research." (PMID 36874021, 2023). "The results showed that CASP4 was located at two sites on the chromosome in which the mean methylation level of CASP4 in PDAC was significantly lower than in para-cancer tissues (P < 0.05)." (PMID 35633405, 2022). "To further explore the mechanism of CASP4 promoting cancer, we knocked down CASP4 by transfection with shRNA in PANC-1 and Aspc-1 cells, and then detected the expression of key enzyme molecules in fatty acid synthesis." (PMID 35633405, 2022). "The expression of ERS-related proteins GRP78, CHOP, IRE1α, XBP-1s, cleaved-caspase-12 and cleaved caspase 4 were also significantly increased in normal cells and cancer cells when treated by 0.1 mg/ml and 1 mg/ml pepsin." (PMID 36309877, 2022). "To further analyse the reasons for the difference in CASP4 expression between cancer and para-cancer, we used DiseaseMeth database to compare the methylation level of CASP4." (PMID 35633405, 2022). "It is noteworthy that CASP4 is commonly known as a cell pyroptosis gene, but it has been found to promote cancer in some experimental and clinical studies, the mechanism of which has not been explored." (PMID 35633405, 2022). "In conclusion, SCGB3A2 uses the machinery of the pyroptotic cell death for the elimination of SDC1/CASP4-positive human cancer cells." (PMID 33452234, 2021). "Therefore, future in vitro and in vivo studies are warranted to explore the detailed mechanism underlying the association between CASP4 expression and ccRCC occurrence and development, to provide direction for further exploration into the mechanism associated with the effects of this gene in cancer." (PMID 33584797, 2020). "Overall, our data support the emerging evidence that inflammatory caspases can regulate cell migration through actin remodeling and uncover a novel role of CASP4 in cancer cell behavior." (PMID 30531914, 2018). "Lungs of mice, injected with tumorigenic CASP4-silenced cells, were characterized by very large nodules, likely due to impaired cell migration and accumulation of cancer cells unable to invade the surrounding tissue." (PMID 30531914, 2018). "Here, we report that downregulation of CASP4 modifies the behavior of human cancer epithelial cell lines by decreasing their cell detachment, cell migration, cell invasion features and increasing actin polymerization and the number and size of focal adhesions." (PMID 30531914, 2018). "Taken together, these results suggest that sequential activation of caspase-4, -2, -8, and -3 is important for SSa-induced cancer cell apoptosis." (PMID 29245990, 2017). "Further studies into possible interactions between the effects of SSa on the NF-κB pathway and the effects of SSa on caspase-4 activation and apoptosis in cancer cells are in progress." (PMID 29245990, 2017).
cancer (continued). "Hemolysin, specifically, plays a crucial role by disrupting the cancer cell membrane, leading to mitochondrial dysfunction and the activation of apoptotic pathways, including caspase-3 and caspase-4, which are more sensitively triggered in cancer cells than in normal cells." (PMID 39728581, 2024). "One study illustrated that CeO2 NPs accelerate the transcription of cytochrome c, which accelerates caspase-3 and caspase-4, which induce apoptosis in cancer cells by targeting mitochondrial proteins, which indirectly reduces the ATP level for cancer cell multiplication." (PMID 35745455, 2022). "The prognostic significance of CASP4 overexpression in cancers remains controversial." (PMID 35633405, 2022). "In order to evaluate whether the circulating caspase-4 was present in other types of cancer, we tested its values in the blood obtained from patients with some solid and liquid tumors." (PMID 29721208, 2018). "Importantly, CASP4-silencing also significantly decreased transwell migration in A431 cells and the other cancer cell lines." (PMID 30531914, 2018). "Inflammatory caspases CASP4 and CASP5 were upregulated in both cell types, correlating with partial activation of inflammation pathways in myoblasts and a robust activation in cancer cells." (PMID 39009887, 2024). "Significantly upregulated PRGs included PYCARD in 12 cancers; GSDMB in 10 cancers; IL18 in 9 cancers; GSDMD, CASP8, GZMB, and GPX4 in 8 cancers; AIM2 and CASP6 in 7 cancers; GZMA in 6 cancers; GSDME, CASP4 and DHX9 in 5 cancers; GSDMA and GSDMC in 4 cancers." (PMID 36605187, 2022). "The pyroptosis regulators with CNV amplification were significantly more highly expressed in cancer cells (e.g., GSDMD), whereas the regulators with CNV deletion were significantly less expressed (e.g., CASP1, CASP3, and CASP4)." (PMID 35620284, 2022). "Among these signatures (TNF, TIRAP, CASP9, PLCG1, PRKACA, CASP3, CASP8, CASP4), TNF (Tumor necrosis factor) is currently considered a two-edged sword in cancer development." (PMID 35741587, 2022). "Our results also suggested that CASP4 was upregulated in HCC and seemed to act as a cancer-promoting gene." (PMID 34820372, 2021). "Based on these results, we propose a new model for SCGB3A2 delivery of LPS and activation of caspase-11(caspase-4) pathway via SDC1 receptor signaling, leading to pyroptosis of cancer cells." (PMID 30526845, 2018). "It had been shown in cancer cells that DHA decreased GRP78 and activated caspase-4, and EPA increased CHOP, respectively." (PMID 30297634, 2018). "Consistent with this, we assessed the mRNA expression levels of SIRT1, EFNB3, and several apoptosis-regulating genes (BIK, CASP3, CASP4, and CASP9) in MCF-7 and MDA-MB-231 cancer cells." (PMID 24489730, 2014). "A third group of cancers comprised of BLCA, BRCA, UCEC, LIHC, STAD, PRAD and THCA showed a similar expression pattern with first group of cancers except for the contrast behavior of NLRP3, NLRC4, PRF1, CASP1, CASP4, and GZMA (downregulated in this group)." (PMID 36605187, 2022). "Therefore, we performed the perturbation expression of pyroptosis regulators across another nearly 10,000 samples, representing 33 cancer types, and observed CASP3, CASP4, CASP8, and GSDMD were highly expressed in cancer cells." (PMID 35620284, 2022). "No significant expression of CASP5 mRNA was detected in all human cancer cell lines examined (data not shown), and therefore we focused on CASP4 in this study." (PMID 33452234, 2021). "Moreover, like selenium, their apoptosis induction effects in cancer cells are also involved with the activation of AMPK and caspase-4, as well as the modulation of ER stress markers, such as CHOP and GRP78." (PMID 30297634, 2018). "Moreover, in our study, circulating caspase-4 was solely detected at high levels (above the cut-off, 0.506 ng/ml) in NSCLC patients compared to some solid and liquid cancer patients, implying high selectivity of the test." (PMID 29721208, 2018).